BTN2A2 (butyrophilin subfamily 2 member A2)
Description:
Inhibits the proliferation of CD4 and CD8 T-cells activated by anti-CD3 antibodies, T-cell metabolism and IL2 and IFNG secretion.
Synonyms: BT2.2; BTF2; BTN2.2
Tractability: Antibody: its Gene Ontology location is reachable by antibodies, with high confidence; UniProt predicts a signal peptide or a membrane-spanning region. PROTAC: ubiquitination databases record sites on it.
Gene: Protein-coding gene on chromosome 6 (26,383,092 to 26,394,880, forward strand). Ensembl gene ENSG00000124508.
Subcellular location: Membrane
Subcellular location (Human Protein Atlas): Mitochondria
Pathways (Reactome):
Immune System: Butyrophilin (BTN) family interactions
Gene Ontology:
Molecular function: protein binding; signaling receptor binding
Biological process: negative regulation of activated T cell proliferation; negative regulation of cytokine production; regulation of cytokine production; T cell receptor signaling pathway
Cellular component: external side of plasma membrane; plasma membrane; cell surface; membrane
Genetic constraint (gnomAD): Loss-of-function variants: 29 observed, 36.17 expected, observed/expected ratio (o/e) 0.8, 90% interval 0.6 to 1.09. The upper end of that interval is the gene's LOEUF score, 1.09, which puts it in group 4 of 6, group 1 being the genes least tolerant of losing a copy. Missense variants: 612 observed, 681.62 expected, observed/expected ratio (o/e) 0.9, 90% interval 0.84 to 0.96. Synonymous variants: 240 observed, 265.48 expected, observed/expected ratio (o/e) 0.9, 90% interval 0.81 to 1.01.
Homologues: Orthologues: chimpanzee BTN2A2 (93% identical), rabbit BTN2A2 (74% identical), guinea pig BTN2A2 (72% identical), dog BTN2A2 (71% identical), mouse Btn2a2 (69% identical), rat Btn2a2 (68% identical). Paralogues in human: BTN2A1 (83% identical), BTN1A1 (48% identical), BTN3A3 (45% identical), BTN3A1 (43% identical), BTNL9 (37% identical), ERMAP (33% identical), BTNL3 (31% identical), BTNL8 (30% identical), BTNL2 (27% identical), BTN3A2 (26% identical), MOG (14% identical), CD276 (13% identical), and 3 more.
Diseases named in the same sentence as BTN2A2 in open-access papers:
BTN2A2 is named in the same sentence as 15 diseases in open-access papers, as found by Europe PMC text mining. Sharing a sentence is not in itself a finding about the gene and the disease. The quoted sentences say what the papers report.
breast carcinoma (4 papers, 2017 to 2025). "The expression level of BTN2A2 is relevant to the clinical outcomes, cell proliferation and migration in breast cancer." (PMID 40936767, 2025).
glioma (4 papers, 2021 to 2025). A benign or malignant brain and spinal cord tumor that arises from glial cells (astrocytes, oligodendrocytes, ependymal cells). "Then, using the ESTIMATE, ssGSEA, and CIBERSORT algorithms, we discovered that BTN2A2 was significantly associated with immune cell infiltration (ICI) in glioma." (PMID 37851374, 2023). "We performed GSEA to determine the underlying mechanisms of BTN2A2 in patients with glioma in our cohort." (PMID 37851374, 2023). "Next, we performed GSEA on our cohort to determine the underlying mechanisms of BTN2A2 in glioma." (PMID 37851374, 2023). "We used bioinformatics analysis to determine the involvement of BTN2A2 in patients with glioma, including CFs, prognosis, and functional analysis." (PMID 37851374, 2023). "In this study, we demonstrated that BTN2A2 expression was significantly high in glioma tissues and cell lines." (PMID 37851374, 2023). "Our analysis showed a significant increase in BTN2A2 expression in patients with glioma from TCGA and GEO cohorts." (PMID 37851374, 2023). "Next, we performed Genes Ontology (GO) and Kyoto Encyclopedia of Genes and Genomes (KEGG) enrichment analyses to understand the mechanism of BTN2A2 in glioma." (PMID 37851374, 2023). "The results demonstrated an increase in BTN2A2 expression was observed with increasing glioma grade." (PMID 37851374, 2023). "The results showed a significant positive correlation between BTN2A2 and immune checkpoint gene expression, thereby indicating the significance of BTN2A2 in the immunotherapy of glioma." (PMID 37851374, 2023). "BTN2A2 is also considered as a potential biomarker and treatment target for glioma." (PMID 40936767, 2025). "Furthermore, IHC analysis demonstrated an increase in BTN2A2 expression in glioma tissues compared to normal brain tissues." (PMID 37851374, 2023). "Our study is the first to determine the involvement of BTN2A2 in glioma, thus suggesting that BTN2A2 could be a therapeutic target for treating patients in the future." (PMID 37851374, 2023). "Finally, we performed immunohistochemistry, growth curve, transwell, and colony formation assays to determine the functions of BTN2A2 in glioma." (PMID 37851374, 2023). "Next, we determined that BTN2A2 was correlated with the prognosis of patients with glioma." (PMID 37851374, 2023). "BTN2A2 regulates glioma development via several immune-related signaling pathways." (PMID 37851374, 2023). "Furthermore, BTN2A2 significantly enhanced the proliferative and migratory abilities of glioma cells." (PMID 37851374, 2023). "Next, we determined the significance of BTN2A2 in predicting the prognosis of patients with glioma." (PMID 37851374, 2023). "In conclusion, our results showed an increase in BTN2A2 expression in glioma cells and tissues." (PMID 37851374, 2023). "Next, we performed qRT-PCR to determine BTN2A2 expression in glioma cell lines." (PMID 37851374, 2023). "Our results showed a high correlation between BTN2A2 and ICIs in patients with gliomas." (PMID 37851374, 2023). "We observed an increase in BTN2A2 expression in glioma cells." (PMID 37851374, 2023). "Together, our results reveal the significance of BTN2A2 in glioma." (PMID 37851374, 2023). "Together, this indicates that BTN2A2 overexpression could promote the proliferative and migratory abilities of glioma cells." (PMID 37851374, 2023). "Together, our results suggest that BTN2A2 could be a therapeutic target for patients with glioma." (PMID 37851374, 2023). "Importantly, our results demonstrated that knockdown of BTN2A2 could significantly inhibit the proliferative and migratory abilities of glioma cells." (PMID 37851374, 2023). "Together, this indicates that BTN2A2 could be a therapeutic target for patients with glioma." (PMID 37851374, 2023). "However, the functions of BTN2A2 in glioma is still unclear." (PMID 37851374, 2023).
glioma (continued). "Further, we observed a significant correlation between BTN2A2 and CFs, such as WHO grade, the status of IDH and 1p/19q codeletion in patients with glioma from TCGA and GEO cohorts." (PMID 37851374, 2023). "High BTN2/3 expression was correlated with OS among sexes (except BTN3A3 in women), WHO grade II (BTN2A2), III (BTN2A2, BTN3A1, and BTN3A2), and IDH-Mut (BTN2A2 and BTN3A2) in glioma." (PMID 36033440, 2022). "Importantly, we showed a correlation between BTN2A2, progression, and ICI in patients with glioma." (PMID 37851374, 2023). "Moreover, BTN2A2 was correlated with progression and ICI in patients with glioma." (PMID 37851374, 2023).
Arthritis (3 papers, 2021 to 2022). Inflammation of a joint. "More recently, involvement was also reported in the regulation of ILC2-T cell crosstalk and bone resorption and reduced levels of soluble Btn2a2 in arthritis of in mouse or BTN2A2 in human arthritis." (PMID 35371078, 2022). "Our results suggest that BTN2A2-Ig protein has the potential to be used in the treatment of collagen-induced arthritis models." (PMID 34588505, 2021). "Moreover, in rheumatoid arthritis patients and experimental arthritis, we detected significantly decreased serum levels of the secreted soluble Btn2a2 protein." (PMID 34421818, 2021).
colon cancer (3 papers, 2016 to 2025). "The frameshift mutation of BTN2A2 might facilitate the pathogenesis of colon cancer via modulating immune response." (PMID 40936767, 2025).
autoimmune disease (2 papers, 2020 to 2021). A disorder resulting from loss of function or tissue destruction of an organ or multiple organs, arising from humoral or cellular immune responses of the individual to their own tissue constituents. "Our results suggest that BTN2A2-Ig protein has the potential to be used in the treatment of autoimmune disease including RA." (PMID 34588505, 2021).
Autoimmunity (2 papers, 2023 to 2024). The occurrence of an immune reaction against the organism's own cells or tissues. "The family member BTN2A2 indeed contributes to the control of T cell activation and proliferation and – accordingly – Btn2a2-knockout mice are more susceptible to T cell-mediated autoimmunity." (PMID 39035010, 2024).
sarcoidosis (1 paper, 2025). Sarcoidosis is a multisystemic disorder of unknown cause characterized by the formation of immune granulomas in involved organs. "Among them, there were 14 genes (ABT1, BTN2A2, C2orf74, CCDC88B, FAM213A, MDH2, METTL21B, PRSS16, RP3-473L9.4, TCF19, TSFM, UBASH3A, UQCC2, ZSCAN26) associated with sarcoidosis risk consistently across these tissues." (PMID 40075078, 2025). "In addition, our TWAS pinpointed many tissue-specific sarcoidosis-associated genes and found expressions of 14 genes (ABT1, BTN2A2, C2orf74, CCDC88B, FAM213A, MDH2, METTL21B, PRSS16, RP3-473L9.4, TCF19, TSFM, UBASH3A, UQCC2, ZSCAN26) associated with sarcoidosis across all three target tissues." (PMID 40075078, 2025).
tumor (6 papers, 2021 to 2025). "The results demonstrated a significant difference in BTN2A2 expression in patients with different tumor grades, tissue categories, and IDH mutations as well as 1p/19q codeletion status." (PMID 37851374, 2023). "During re-infusion therapy, the BTN2A2 antibodies were leveraged to inhibit the proliferation of Tregs and MDSCs within the tumor." (PMID 40026625, 2025). "Subsequent to the return treatment, BTN2A2 antibody on the surface of the droplet inhibited the proliferation of Tregs and MDSCs in the tumor, and CMP within the droplet increased the ability of T cells to infiltrate the tumor microenvironment." (PMID 40026625, 2025). "This preparation was surface modified with BTN2A2 antibodies and internally contained T cells isolated from the blood of tumor hosts, along with simulated collagen peptide CMP." (PMID 40026625, 2025). "The expression of several butyrophilin (BTN) and butyrophilin-like (BTNL) molecules was significantly altered by inflammation, including BTN1A1, BTN2A2, BTN3A3, and BTNL831, and associated with tumor development." (PMID 37369724, 2023). "We determined the difference in BTN2A2 expression in tumor and normal tissues using the differential gene expression module of TIMER." (PMID 37851374, 2023). "A significant correlation between the effect of BTN2A2 on the patient prognosis and age, the status of IDH mutation, 1p/19q co-deletion, tumor grade, primary therapy outcome, and type of tumor tissues." (PMID 37851374, 2023). "Nevertheless, the role and the mechanisms of BTN2A2 in tumor onset and progression are yet to be determined." (PMID 37851374, 2023). "It had been discovered that the expression of BTN2A2 by tumor cells could inhibit the proliferation of activated CD8+ T cells and promote the proliferation of Tregs and MDSCs." (PMID 40026625, 2025). "We observed an increase in BTN2A2 expression levels with an increase in the patient’s tumor grade." (PMID 37851374, 2023). "This suggests that the combined therapy impairs tumor cell survival strategies such as DNA damage response, metabolic maintenance, and immune function (including CCR3, SPNS3, SPPL3, and BTN2A2)." (PMID 41404060, 2025).
cancer (4 papers, 2018 to 2025). A tumor composed of atypical neoplastic, often pleomorphic cells that invade other tissues. "BTN2A2, an immunoregulatory gene of the butyrophilin family, has inhibitory effects on T cell activation and is implicated in immune tolerance in cancers." (PMID 40936767, 2025). "The results showed BTN2A2 was associated with the CTLA4, MHC, chemokine, JAK-STAT signaling pathways, antigen processing and presentation, PD1 blockade cancer immunotherapy, immune cells-microRNAs interactions in the TME, and apoptosis." (PMID 37851374, 2023). "Aberrant BTN2A2 expression in various cancers indicates that BTN2A2 could be an important cancer biomarker." (PMID 37851374, 2023). "Next, we performed a transwell assay to determine if BTN2A2 could regulate the migration of cancer cells." (PMID 37851374, 2023).
infection (2 papers, 2022). The state of being infected such as from the introduction of a foreign agent such as serum, vaccine, antigenic substance or organism. "Hence, Btn2a2 acts as effective T cell-inhibiting molecule on ILC2, which is induced by infection or during inflammation." (PMID 35145516, 2022).
BTN2A2 also shares sentences with these, for which no sentence is quoted: rheumatoid arthritis (2 papers); experimental autoimmune encephalomyelitis (1); helminth infections (1); lung carcinoma (1); ulcerative colitis (1).